MET (MET proto-oncogene, receptor tyrosine kinase)
Diseases named in the same sentence as MET in open-access papers (continued):
Sharing a sentence is not in itself a finding about the gene and the disease.
pancreatic cancer (continued). "Activated PSCs secreted HGF, which resulted in increased c-mesenchymal-epithelial transition (c-MET) expression and enhanced antioxidant capacity in pancreatic cancer cells." (PMID 35693705, 2022). "CircRNA PDE8A in sEVs can promote the occurrence and development of pancreatic cancer through Mir-338 /MACC1/MET pathway, which has a significant role in the progression of pancreatic cancer and can be as a potential biomarker." (PMID 34980146, 2022). "The GEPIA database showed that c-MET expressed a higher level in human pancreatic cancer than the normal pancreatic tissues." (PMID 35693705, 2022). "The MET gene plays an important role in the proliferation and progression of pancreatic cancer through the hepatocyte growth factor (HGF)/C-MET axis." (PMID 35865013, 2022). "c-MET-IN-1 significantly enhanced the sensitivity of pancreatic cancer cells to ferroptosis and reduced cell survival." (PMID 35693705, 2022). "In this regard, the HGF/c-MET axis had a vital role in the defense of pancreatic cancer cells against ferroptosis." (PMID 35693705, 2022). "Our primary results also implied that the HGF/c-MET axis affects the antioxidant capacity of pancreatic cancer cells and thus the ferroptosis sensitivity of the cells, which is according to a previous publication." (PMID 35693705, 2022). "We identified 7 highly expressed pancreatic cancer cell surface receptors (MET, NPR3, IL1RAP, SLC2A1, SLC6A6, GABRP, and TMPRSS4) in all the analyzed datasets." (PMID 35359382, 2022). "Mechanistically, activated PSCs secreted HGF, which further activated the HGF receptor, c-MET, in pancreatic cancer cells, prevented lipid peroxidation, and ultimately triggered pancreatic cancer cell ferroptosis resistance in vitro and in vivo." (PMID 35693705, 2022). "Erastin and RSL3 induced more c-MET-knockdown pancreatic cancer cell death under coculture conditions or in the presence of HGF." (PMID 35693705, 2022). "In view of these findings, there is continuous research on targeting HGF-MET signaling in pancreatic cancer with MET overexpression." (PMID 34479614, 2021). "DCLK1 has previously been linked to the pro-oncogenic CSC markers c-MET and c-MYC, and gene set enrichment analysis demonstrated that DCLK1-IN-1 affected MET-driven oncogenesis in patient-derived pancreatic cancer organoids." (PMID 34830884, 2021). "Our results suggest it has excellent potential to overcome the limitations of current treatments for pancreatic cancer, including currently available c-MET-targeting therapies." (PMID 33816276, 2021). "MET, OAS1, and OASL mRNAs were all up-regulated in pancreatic cancer and associated with unfavorable prognosis." (PMID 33869254, 2021). "Among these genes, MET, OAS1, and OASL were validated to be up-regulated in pancreatic cancer and associated with unfavorable prognosis of patients." (PMID 33869254, 2021). "The c-MET expression levels in pancreatic cancer cell lines were significantly increased compared to the expression in HPNE cells, particularly in Aspc-1 cells." (PMID 33816276, 2021). "In this study, we investigated the effect of HGF/MET axis modulation on pancreatic-cancer-cell signature, focusing on the differential expression of TNC." (PMID 34298732, 2021). "We found that 17 RTKs, including MET, were significantly upregulated in pancreatic cancer tissues compared with normal pancreatic tissue, suggesting that they are potentially viable therapeutic targets." (PMID 34479614, 2021). "Consistently, MET was up-regulated in pancreatic cancer both in the GSE15471 (p = 1.002e-09) and GSE62452 datasets (p = 2.792e-11)." (PMID 33869254, 2021). "Among them, MET, OAS1, and OASL were verified to be markedly up-regulated in pancreatic cancer and associated with poor clinical outcomes of patients." (PMID 33869254, 2021). "In conclusion, this study showed that dual blocking of MET and PD-L1 enhances pancreatic cancer immunotherapy." (PMID 34479614, 2021).
pancreatic cancer (continued). "Correlation between c-MET expression and clinicopathological features of patients with pancreatic cancer." (PMID 33816276, 2021). "Clinical studies have shown that elevated c-MET expression has prognostic value for many types of epithelial cancers (including pancreatic cancer)." (PMID 33816276, 2021). "This study provides several key advances, as follows: We have verified the role of c-MET targeting ADC drugs in pancreatic cancer in vivo and in vitro for the first time." (PMID 33816276, 2021). "The expression of c-MET in pancreatic tumour tissues is 5-7-fold higher than that of adjacent tissues, which creates a large therapeutic safety window for ADCs targeting c-MET." (PMID 33816276, 2021). "Among 21 genes from the immune-related signature, MET, OAS1, and OASL were significantly associated with prognosis of pancreatic cancer patients." (PMID 33869254, 2021). "To understand how inhibition of the HGF/MET pathway in pancreatic cancer cells influences stroma activation, we performed a transcriptome analysis by RNA-sequencing-based gene expression analysis (RNAseq)." (PMID 34298732, 2021). "In our results, we concluded that MET was the important factor in the effects of Amatuximab by mesothelin blockage in pancreatic cancer cells." (PMID 33637083, 2021). "The hepatocyte growth factor and its receptor, c-MET play an important role in cancer progression (as discussed in detail below), and this pathway warrants investigation for its role in pancreatic cancer." (PMID 33271944, 2020). "HGF is produced by PSCs and its receptor c-MET is expressed on pancreatic cancer cells and endothelial cells." (PMID 33271944, 2020). "There have been some encouraging data pertinent to HGF and/or c-MET inhibitors in clinical trials (mostly phase I/II trials) in several non-pancreatic cancers." (PMID 33271944, 2020). "Given that a majority of patients are diagnosed at an advanced stage, it would be essential to investigate the effect of HGF/c-MET inhibition in combination with gemcitabine in a model of advanced pancreatic cancer." (PMID 32203220, 2020). "While cancer-associated PSCs secrete hepatocyte growth factor (HGF), its receptor c-MET is present on pancreatic cancer cells." (PMID 32116785, 2020). "Its clinical relevance to pancreatic cancer has also been demonstrated, with various studies reporting on the overexpression of MET in pancreatic cancers and a correlation between elevated serum levels of HGF and aggressive PDAC phenotypes." (PMID 32485915, 2020). "In pancreatic cancer patients, elevated serum HGF levels have been reported to correlate with disease progression, and tumour expression of c-MET to be associated with poor survival." (PMID 33271944, 2020). "In the present study, we found increased RON and MET expression in pancreatic cancer tissues, and RON and MET expression were highly correlated." (PMID 31867280, 2019). "We assume that RON and MET are suitable targets in pancreatic cancer treatment, and new therapy will further increase survival." (PMID 31867280, 2019). "Tyrosine kinase inhibitors targeting RON and MET in pancreatic cancer are a novel and potential approach for pancreatic cancer therapy." (PMID 31867280, 2019). "TKIs targeting RON and MET have a better inhibitory effect on pancreatic cancer cell in vivo and vitro experiment." (PMID 31867280, 2019). "The role of RON and MET in pancreatic cancer malignant progression, angiogenesis, and chemoresistance has also been studied extensively via genetic, biochemical, and biological models." (PMID 31867280, 2019). "Tivantinib exhibited a good inhibitory effect on pancreatic cancer cells independently of MET inhibition." (PMID 31867280, 2019). "The cell lines have previously been used to determine the role of RON and MET in regulating pancreatic cancer tumorigenic activity." (PMID 31867280, 2019). "MET aberrant activation in pancreatic cancer is involved in the onset of resistance to gemcitabine by different mechanisms." (PMID 30544501, 2018).
pancreatic cancer (continued). "On one side, MET has been identified as a marker of pancreatic cancer stem cells (CSCs), and on the other the MET/HGF axis supports the mesenchymal network." (PMID 30544501, 2018). "Our list identified several genes that have been found to be activated in pancreatic cancer such as MET, MAP4K4, and ITGA2." (PMID 30092011, 2018). "Since the pioneer studies published in 1995, the MET/HGF system has gained growing attention with respect to its role in the pathogenesis of pancreatic cancer." (PMID 30544501, 2018). "Here, we discuss the role of the MET/HGF axis in tumor progression and dissemination considering as a model pancreatic cancer, and provide a proof of concept for the application of dual MET/HGF inhibition as an adjuvant therapy in pancreatic cancer patients." (PMID 30544501, 2018). "b) reduction of uPA production by cancer cells, thus preventing further HGF activation (thus inhibiting the positive feedback loop).c) blockade of stemness in cancer cells (given that c-MET is recognized to be a stem cell marker in pancreatic cancer)." (PMID 29100344, 2017). "Using both in vivo and in vitro approaches, this study has provided novel evidence to indicate that stromal reprogramming (by inhibiting the HGF/c-MET pathway) combined with chemotherapy significantly reduces pancreatic cancer progression." (PMID 29100344, 2017). "The proto-oncogene c-MET, a bona fide therapeutic target in human malignancies, including pancreatic cancer, is upregulated in KRAS-mutant SW48 cells versus isogenic controls." (PMID 28807782, 2017). "Specific inhibition of RON enhanced c-MET signaling leading to delayed tumor progression in a pancreatic cancer model." (PMID 26872377, 2016). "HIF-dependent pathways activate MET in pancreatic tumor cells, while stroma-secreted HGF facilitates cell motility from the hypoxic regions of the tumors to the oxygen-rich distant organs." (PMID 26404380, 2015). "With such compelling evidence, NK4 is a plausible option to target HGF along with c-MET and other drugs currently in use for controlling pancreatic cancer." (PMID 26404380, 2015). "Because the HGF/c-MET signaling is one of the most frequently dysregulated pathways in pancreatic cancer, targeting of this pathway received much attention recently." (PMID 25909285, 2015). "Other groups have also shown that MET silencing results in the impaired growth of other tumors, e.g., gastric and pancreatic carcinomas." (PMID 25888626, 2015). "Pancreatic cancer cells with a high expression of both c-MET and CD44 were shown to have a greater tumorigenic potential." (PMID 24823486, 2014). "c-MET inhibitors, including Crizotinib and Cabozantinib, enhanced the antitumor effect of gemcitabine in pancreatic cancers." (PMID 25193856, 2014). "Recently, c-MET has been identified as a new marker for pancreatic stem cells and therapeutic target in pancreatic cancer." (PMID 25193856, 2014). "PAX6 is also a regulator of MET tyrosine kinase receptor expression in pancreatic carcinoma cell lines." (PMID 24454925, 2014). "A recent study showed that PAX6 promotes cell growth by activating the MET tyrosine kinase receptor gene in pancreatic carcinoma." (PMID 24454925, 2014). "In pancreatic tumor samples, the expression of HIF-1α was correlated with upregulation of c-MET and its ligand hepatocyte growth factor (HGF) in both pancreatic cancer cells and stromal cells, and is linked with an increase in lymph node metastases." (PMID 24213498, 2012). "The HGF/c-MET (mesenchymal–epithelial transition factor) pathway is emerging as a key area of focus in understanding and potentially disrupting the intricate cellular interaction that results in pancreatic cancer’s aggressiveness and resistance to treatment." (PMID 38473413, 2024). "Additionally, c-MET activation has been reported to increase resistance to chemotherapy, tumor cell motility, and the secretion of angiogenic factors in patients with pancreatic cancer." (PMID 38473413, 2024).
pancreatic cancer (continued). "Thus, targeting the FOXM1–HGF/MET axis is considered an opportunity to develop new anticancer drugs for pancreatic cancer." (PMID 39594778, 2024). "Many MET inhibitors are now being researched for the treatment of pancreatic cancer." (PMID 39000029, 2024). "Studies of other MET tyrosine kinase inhibitors, such as crizotinib, cabozantinib, and capamatinib, for pancreatic cancer have suggested that trametinib may be effective in treating pancreatic cancer." (PMID 38473413, 2024). "Therefore, targeting the HGF/c-MET signaling pathway appears promising for the development of innovative drugs for pancreatic cancer treatment." (PMID 38473413, 2024). "Additionally, elevated MET and PD‐L1 expression have been strongly associated with lymph node metastasis, tumor TNM staging, and overall survival in pancreatic cancer." (PMID 38077251, 2023). "As such, the MET inhibitors plus immune checkpoint inhibitors (ICIs) strategy has been improving pancreatic cancer immunotherapeutic efficacy, evidencing potential crosstalk between c-MET inhibition and immune escape since PD-L1 expression positively correlates with METamp." (PMID 36430388, 2022). "In addition, the role of exosomes circRNA circ‐PDE8A in regulating the invasion of pancreatic cancer through the miR‐338/MACC1/MET pathway has also been described." (PMID 35446993, 2022). "However, MET was also described to be regulated by other mechanisms, such as the hypomethylation of its promoter in pancreatic cancer, and more than 30 microRNAs regulating MET expression, including miR-34a, downregulated in ESCC (30, –32)." (PMID 34037097, 2021). "Exosomal circRNA PDE8A promotes pancreatic cancer invasion via the miR-338/MACC1/MET pathway." (PMID 33867829, 2021). "This study systematically investigated the potential effectiveness of a novel pancreatic cancer immunotherapy targeting RTKs, and revealed the function of MET in PD-L1 regulation as well as the combined therapeutic efficacy of MET and PD-L1 in pancreatic cancer." (PMID 34479614, 2021). "We then examined MET and PD-L1 levels in tumor tissue microarray from 140 PDAC patients and found that approximately 68 % specimens with high MET expression levels exhibited intense PD-L1 staining, confirming the positive correlation between them in pancreatic cancer." (PMID 34479614, 2021). "Additionally, the dysregulation of circ-PDE8A in exosomes has been found to contribute to the invasive growth of pancreatic cancer through the MACC/MET/ERK/Akt signaling pathway." (PMID 34486489, 2021). "Finally, significant benefits of combining MET inhibition with PD-1/PD-L1 blockage were verified in both orthotopic and subcutaneous mouse models of pancreatic cancer." (PMID 34479614, 2021). "To analyze whether such a correlation might exist, we downloaded the data on GLRX3 and MET mRNA expression levels in human pancreatic cancers available at The Cancer Genome Atlas (TCGA)." (PMID 34794402, 2021). "Therefore, targeting c-MET through SHR-A1403 showed strong preclinical anti-tumour efficacy in pancreatic cancer." (PMID 33816276, 2021). "c-MET activation has been reported to increase: resistance to gemcitabine therapy; tumour cell motility; and secretion of angiogenic factors in pancreatic cancer." (PMID 33271944, 2020). "The authors envision that a novel antiangiogenic approach that targets the HGF/c-MET and uPA pathways could be used against pancreatic cancer." (PMID 32116785, 2020). "c-MET reportedly is a stem cell marker in pancreatic cancer." (PMID 33271944, 2020). "We demonstrate clearly that RON and MET can be new therapeutic targets in pancreatic cancer." (PMID 31867280, 2019). "Here, we explored RON and MET expression in pancreatic cancer and their relationship with overall survival (OS) time, and evaluated their significance as therapeutic targets of tyrosine kinase inhibitors in pancreatic cancer." (PMID 31867280, 2019). "Compared to RON, MET was more widely overexpressed in pancreatic cancer tissues." (PMID 31867280, 2019).
pancreatic cancer (continued). "RON and MET may be involved in the malignant process of pancreatic cancer, and can serve as a biomarker for evaluating the prognosis of patients with pancreatic cancer." (PMID 31867280, 2019). "BMS777607 and PHA665752, both targeting RON and MET, could inhibit pancreatic cancer cell viability and migration and induce apoptosis effectively." (PMID 31867280, 2019). "We explored RON and MET expression in pancreatic cancer and their relationship with survival time to investigate whether they can be used as a new prognostic marker in pancreatic cancer." (PMID 31867280, 2019). "RON and MET expression are highly correlated with OS in pancreatic cancer." (PMID 31867280, 2019). "In conclusion, RON and MET are widely expressed in pancreatic cancer tissues." (PMID 31867280, 2019). "In addition, CD44v6 can promote pancreatic cancer growth and metastasis through the MET and VEGFR2 pathway, and pre-metastatic niche formation induced by exosomes requires CD44v6." (PMID 30060755, 2018). "In addition, synergistic combination of tivantinib and gemcitabine also show antitumor activity in cells highly expressing c-MET in pancreatic cancer." (PMID 30360560, 2018). "Moreover, NEAT1, a nuclear-restricted long noncoding RNA, suppresses the microRNA-335-5p/c-MET axis to promote pancreatic cancer malignancy." (PMID 30360560, 2018). "HGF is produced by PSCs and its receptor c-MET is expressed on pancreatic cancer cells." (PMID 29100344, 2017). "Several studies have linked activation of c-MET signalling to phosphorylation of intracellular signalling cascades such as PI3K/AKT, MAPK/ERK or FAK in pancreatic cancer models, leading to tumor cell invasiveness, motility and resistance to gemcitabine therapy." (PMID 29100344, 2017). "However, Foretinib only showed significant anti-cancer activity at high concentration reflecting the intrinsic chemoresistance of pancreatic cancer cells and additional RTKs beside c-MET are important for the proliferation and survival of these cancer cells." (PMID 25909285, 2015). "We propose that an in-depth analysis of the HGF/c-MET signaling system in pancreatic cancer could bridge the gap between basic biology and translational medicine." (PMID 26404380, 2015). "Over-expression of HGF and c-MET was detected in a high proportion of pancreatic cancer." (PMID 25909285, 2015). "Interestingly, in colon cancer cell lines MET has been identified as a direct transcriptional target of β-catenin and in pancreatic cancer MET has been recognized as a cancer stem cell marker." (PMID 25536063, 2014). "In addition, c-MET inhibitor, such as Cabozantinib, has overcome gemcitabine resistance in pancreatic cancer cells." (PMID 25193856, 2014). "C-MET and p-c-MET were highly expressed in pancreatic cancer cell lines." (PMID 25193856, 2014). "Recent studies have reported that c-MET was considered as a potential target in pancreatic cancer." (PMID 25193856, 2014). "Furthermore, treatment of mice bearing xenograft pancreatic tumors with a c-MET inhibitor XL184 reduced tumor growth, especially in combination with gemcitabine." (PMID 24213498, 2012). "Moreover, inhibition of the HGF/MET axis could be combined with chemotherapeutics agents, as proposed in a preclinical study for pancreatic cancer treatment." (PMID 37345079, 2023). "Thus, targeting MET has been considered as an adjuvant therapy in pancreatic cancer." (PMID 33869254, 2021). "Notably, HGF/c-MET inhibition has been shown in preclinical models to increase drug delivery and improve chemotherapeutic response both in genetically engineered mouse models and orthotopic models of pancreatic cancer." (PMID 33271944, 2020). "Another MET inhibitor Crizotinib could prevent peritoneal dissemination in pancreatic cancer." (PMID 30126419, 2018). "Moreover, the MET/HGF co-targeting may represent an option as an adjuvant therapy in pancreatic cancer." (PMID 30544501, 2018).